ECM1 (extracellular matrix protein 1)
Diseases named in the same sentence as ECM1 in open-access papers (continued):
Sharing a sentence is not in itself a finding about the gene and the disease.
infection (6 papers, 2016 to 2024). The state of being infected such as from the introduction of a foreign agent such as serum, vaccine, antigenic substance or organism. "Moreover, elevated levels of keratin (K22E) and ECM1 in the plasma of patients during early infection indicate active tissue damage and remodeling due to the SARS-CoV-2 infection." (PMID 38672194, 2024). "CAG:581 infection accelerated the proliferation of NMIBC organoids (p < 0.01); ECM1 and MMP9 were the most upregulated genes induced by the increased colony forming units (CFU) gradient of Eubacterium sp." (PMID 36765767, 2023). "The order of virulence ability we observed from greatest to least, WT, ecm1, nuc1, and ecm1 nuc1, fits with the notion that deletion of NUC1 critically impacts ability to digest plant-secreted DNA and thus, infection." (PMID 30837342, 2019). "To evaluate the role of ECM1 in the regulation of HCC cells migration, we carried out a wound healing assay at 24 h post-infection." (PMID 27460906, 2016).
genodermatosis (4 papers, 2019 to 2024). "ECM1 thus penetrates into the fundamental skin biology via complex organization with surrounding microstructural molecules, and mutations of their corresponding genes are responsible for a hereditary genodermatosis LiP." (PMID 36553077, 2022).
genetic diseases (2 papers, 2021 to 2022). "Extracellular matrix protein 1 (ECM1) is a secreted protein and its mutations can lead to the genetic disorder lipoid proteinosis." (PMID 33644779, 2021).
ECM1 also shares sentences with these, for which no sentence is quoted: glioma (3 papers); lichen sclerosus (3); atopic dermatitis (2); frontotemporal dementia (2); Inguinal hernia (2); invasive breast ductal carcinoma (2); osteoarthritis (2); abdominal hernia (1); acute kidney injury (1); acute lung injury (1); allergic rhinitis (1); alopecia areata (1); Alzheimer disease (1); amyotrophic lateral sclerosis (1); B-cell acute lymphoblastic leukemia (1); brain disorder (1); brain tumour (1); Brugada syndrome (1); cardiac disease (1); cardiomyopathy (1); Chagas disease (1); Cornelia de Lange syndrome (1); COVID-19 (1); demyelinating central nervous system disease (1); diabetes (1); diabetic retinopathy (1); diverticulitis (1); Doyne honeycomb retinal dystrophy (1); eczema (1); endometrial cancer (1).
A further 44 diseases each share a sentence with ECM1 in 1 paper.